ATP7A (ATPase copper transporting alpha)
Description:
ATP-driven copper (Cu(+)) ion pump that plays an important role in intracellular copper ion homeostasis. Within a catalytic cycle, acquires Cu(+) ion from donor protein on the cytoplasmic side of the membrane and delivers it to acceptor protein on the lumenal side. The transfer of Cu(+) ion across the membrane is coupled to ATP hydrolysis and is associated with a transient phosphorylation that shifts the pump conformation from inward-facing to outward-facing state. Under physiological conditions, at low cytosolic copper concentration, it is localized at the trans-Golgi network (TGN) where it transfers Cu(+) ions to cuproenzymes of the secretory pathway. Upon elevated cytosolic copper concentrations, it relocalizes to the plasma membrane where it is responsible for the export of excess Cu(+) ions. May play a dual role in neuron function and survival by regulating cooper efflux and neuronal transmission at the synapse as well as by supplying Cu(+) ions to enzymes such as PAM, TYR and SOD3 (By similarity). In the melanosomes of pigmented cells, provides copper cofactor to TYR to form an active TYR holoenzyme for melanin biosynthesis (By similarity).
Synonyms: MNK; DSMAX; HMNX; MK; SMAX3
Tractability: Small molecule: a structure with a bound ligand is known. Antibody: UniProt places it where antibodies can reach, with high confidence; its Gene Ontology location is reachable by antibodies, with high confidence; UniProt predicts a signal peptide or a membrane-spanning region. PROTAC: ubiquitination databases record sites on it; its protein half-life has been measured.
Safety:
Unwanted effects reported when the protein is acted on. In parentheses: how it was acted on, where the effect was seen, and who reports it.
drug toxicity (source: ClinPGx)
Gene: Protein-coding gene on chromosome X (77,910,690 to 78,050,395, forward strand). Ensembl gene ENSG00000165240.
Subcellular location: Golgi apparatus, trans-Golgi network membrane; Cell membrane; Melanosome membrane; Early endosome membrane; Cell projection, axon; Cell projection, dendrite; Postsynaptic density; Cytoplasm, cytosol (Isoform 3); Endoplasmic reticulum (Isoform 5)
Subcellular location (Human Protein Atlas): Golgi apparatus
Pathways (Reactome):
Cellular responses to stimuli: Detoxification of Reactive Oxygen Species
Immune System: Ion influx/efflux at host-pathogen interface
Transport of small molecules: Ion transport by P-type ATPases
Gene Ontology:
Molecular function: ATP binding; copper ion binding; copper ion transmembrane transporter activity; copper-dependent protein binding; cuprous ion binding; P-type monovalent copper transporter activity; protein binding; P-type divalent copper transporter activity; superoxide dismutase copper chaperone activity; ATP hydrolysis activity; ATPase-coupled monoatomic cation transmembrane transporter activity; metal ion binding; nucleotide binding
Biological process: copper ion export; copper ion transport; intracellular copper ion homeostasis; positive regulation of melanin biosynthetic process; regulation of removal of superoxide radicals; blood vessel development; blood vessel remodeling; cartilage development; catecholamine metabolic process; central nervous system neuron development; cerebellar Purkinje cell differentiation; collagen fibril organization; copper ion import; detoxification of copper ion; dopamine metabolic process; elastic fiber assembly; epinephrine metabolic process; extracellular matrix organization; glycoprotein biosynthetic process; hair follicle morphogenesis; locomotory behavior; lung alveolus development; mitochondrion organization; neuron projection morphogenesis; norepinephrine metabolic process; and 8 more
Cellular component: basolateral plasma membrane; endoplasmic reticulum; Golgi apparatus; late endosome; membrane; perinuclear region of cytoplasm; plasma membrane; trans-Golgi network; trans-Golgi network membrane; trans-Golgi network transport vesicle; axon; dendrite; early endosome membrane; melanosome membrane; neuron projection; neuronal cell body; phagocytic vesicle membrane; postsynaptic density; bounding membrane of organelle; cytoplasmic vesicle; cytoplasmic vesicle membrane; cytosol; endosome
Gene-disease validity (ClinGen):
ClinGen rates the evidence that ATP7A causes each of these diseases.
Menkes disease (X-linked): Definitive. A usually severe multisystemic disorder of copper metabolism, characterized by progressive neurodegeneration and marked connective tissue anomalies as well as typical sparse abnormal steely hair.
X-linked distal spinal muscular atrophy type 3 (X-linked): Moderate.
Homologues: Orthologues: chimpanzee ATP7A (99% identical), macaque ATP7A (98% identical), dog ATP7A (92% identical), rabbit ATP7A (92% identical), pig ATP7A (92% identical), mouse Atp7a (89% identical), rat Atp7a (89% identical), guinea pig ATP7A (87% identical), tropical clawed frog atp7a (68% identical), zebrafish atp7a (65% identical), Caenorhabditis elegans cua-1 (37% identical), Caenorhabditis elegans pmr-1 (11% identical), and 7 more. Paralogues in human: ATP7B (55% identical), ATP2B3 (15% identical), ATP2B2 (14% identical), ATP2B4 (14% identical), ATP2B1 (14% identical), ATP1A2 (14% identical), ATP1A1 (13% identical), ATP2A2 (13% identical), ATP2A1 (13% identical), ATP1A4 (13% identical), ATP1A3 (13% identical), ATP2A3 (13% identical), and 9 more.
Diseases named in the same sentence as ATP7A in open-access papers:
ATP7A is named in the same sentence as 167 diseases in open-access papers, as found by Europe PMC text mining. Sharing a sentence is not in itself a finding about the gene and the disease. The quoted sentences say what the papers report.
Menkes disease (164 papers, 2008 to 2026). "Mutations in the copper (Cu) transporter ATP7A cause a spectrum of X-linked diseases, including Menkes Disease, Occipital horn syndrome and distal hereditary motor neuropathy (dHMNX)." (PMID 42247602, 2026). "Menkes disease is an X-linked disorder caused by ATPase copper transporting alpha (ATP7A) mutations on Xq13.3, leading to impaired copper transport." (PMID 41480765, 2026). "Menkes disease (MD) is a rare X-linked recessive disorder caused by mutations in the ATP7A gene, leading to impaired copper transport and deficiency of essential copper-dependent enzymes." (PMID 42254141, 2026). "ATP7A, a P-type copper-transporting ATPase, regulates intracellular copper homeostasis, and its mutations cause lethal infantile Menkes disease." (PMID 41480765, 2026). "In humans, mutations in Atp7a are linked to Menkes disease, a disease with pleiotropic and severe neurological phenotypes." (PMID 40678754, 2025). "The mutation of the same residue in paralogous ATP7A causes Menkes disease, the pathogenic effect most probably associated with the disruption of the phosphotransfer reaction that is common for both ATP7A and ATP7B." (PMID 40661833, 2025). "Here, we generated plasmids encoding the MS2 system and the APOBEC1 deaminase domain and used a guide RNA with flanking MS2 sites to restore mutated Atp7a in fibroblasts from a macular mouse model of Menkes disease withs T>C mutation." (PMID 39858530, 2025). "In conclusion, our findings expand the mutational spectrum of ATP7A by identifying a novel retrotransposition-derived, exon-disrupting retropseudogene insertion as a pathogenic cause of Menkes disease." (PMID 41393994, 2025). "Three male Labrador Retrievers and two male crossbreed dogs were hemizygous for the ATP7A variant associated with Menkes disease." (PMID 40151526, 2025). "Menkes disease is a recessive X-chromosome-linked hereditary syndrome in humans, caused by defective copper metabolism due to mutations in the ATP7A gene, which encodes a copper transport protein." (PMID 39858530, 2025). "Menkes syndrome is an X-linked recessive disorder caused by mutation in gene coding for ATP7A, leading to copper deficiency." (PMID 41009734, 2025). "These variants cause hypotonia, developmental delay, seizures, and low serum copper/ceruloplasmin, situating hCTR1 deficiency, similar to the effect of ATP7A mutations in Menkes disease on the copper-deficiency spectrum but upstream of ATP7A." (PMID 41463392, 2025). "The disease manifestations in the Menkes disease patient with a somatic mosaicism for the inactivating ATP7A P1001L mutation further support the importance of ATP7A-mediated Cu export from ChPl." (PMID 39172219, 2025). "Mottled brindled mice have a two-amino-acid deletion in the transmembrane segment 4 of Atp7a and recapitulate major aspects of human Menkes disease, including brain Cu deficiency." (PMID 39172219, 2025). "Pathogenic variants in the ATP7A gene, which encodes a transmembrane copper-transporting P-type ATPase, underlie Menkes disease, a rare X-linked recessive disorder of copper metabolism." (PMID 41393994, 2025). "Although none of the dogs had clinical symptoms related to any of these diseases when the samples were collected, three Labrador Retrievers and two cross breed dogs were hemizygously affected for Menkes disease due to a missense variant in the ATP7A gene." (PMID 40151526, 2025). "Menkes syndrome is an extremely rare congenital disorder of copper metabolism caused by variants in the ATP7A gene and follows an X-linked recessive inheritance pattern." (PMID 40689217, 2025). "A more recent study using the Genome Aggregation Database (gnomAD) and frequency of pathogenic ATP7A alleles predicted a much higher occurrence of Menkes disease in the US population: 1 in 34,810 live male births." (PMID 39172219, 2025). "Menkes syndrome is a rare X-linked genetic disorder of copper metabolism caused by variants in the ATP7A gene." (PMID 40689217, 2025).
Menkes disease (continued). "These pathogenic variants correspond to the p.Thr994Ile and Pro1386Ser pathogenic variants in ATP7A, which cause severe Menkes disease." (PMID 38397079, 2024). "Pathogenic variants in ATP7A, which is ubiquitously expressed and abundant in enterocytes, lead to systemic deficiency of copper, causing Menkes disease (Tümer and Møller, 2010)." (PMID 38032054, 2024). "Mutations in the gene encoding ATP7A lead to Menkes disease, which is characterized by a severe systemic copper deficiency, as the export of Cu from enterocytes (basolateral membrane) to portal blood is impaired." (PMID 38727263, 2024). "The resulting loss of functional ATP7A in the intestine of patients with Menkes disease leads to an accumulation of copper in enterocytes and follows reduced copper efflux into the blood." (PMID 38731973, 2024). "Menkes disease (MD) is an abnormality of copper metabolism caused by an X-linked recessive genetically inherited abnormality of the ATP7A gene." (PMID 39717303, 2024). "For genetic diseases: Menkes disease and Wilson disease, caused by mutations in ATP7A/7B gene, generalize severe organ Cu deficiency or overload." (PMID 39659361, 2024). "Menkes disease is an X-linked recessive genetically inherited metabolic disease caused by an ATP7A gene abnormality that gives rise to impaired copper absorption." (PMID 39717303, 2024). "Menkes disease (MIM 309400) is a rare X-linked copper metabolism disease caused by pathogenic variants in ATP7A (MIM 300011)." (PMID 38141875, 2024). "A pathogenic variant in ATP7A gene was identified in the patient, so he was confirmed the diagnosis of Menkes disease." (PMID 38926644, 2024). "The fundamental requirement for copper in neurological function is exemplified by Menkes disease where mutations affecting the copper transporter ATP7A result in systemic copper deficiency, cuproenzyme dysfunction, neurodegeneration, and premature death." (PMID 39164165, 2024). "Mutation in the ATP7A gene causes Menkes disease/syndrome, X-linked recessive genetic disorder, and a severe form of copper deficiency, with very early onset in infancy." (PMID 39518128, 2024). "Copper deficiency, often caused by mutations in the ATP7A gene, results in Menkes disease, an X-linked recessive disorder." (PMID 39518128, 2024). "Menkes disease is caused by the mutations in the gene ATP7A responsible for the synthesis of the copper-binding ATP7A protein." (PMID 38248841, 2024). "A mutation in the ATP7A gene is the cause of Menkes disease, it prevents the supply of copper ions to enzymes dependent on them, such as dopamine β-hydroxylase and lysyl oxidase." (PMID 38248841, 2024). "We describe here a 7-month-old female patient with Menkes disease caused by partial deletion of the ATP7A gene inherited from her mother and her grandmother." (PMID 38172222, 2024). "Menkes disease is an X-linked disorder of copper metabolism caused by mutations in the ATP7A gene, and female carriers are usually asymptomatic." (PMID 38172222, 2024). "Low CP and/or the pancytopenia have been recognized in patients with copper deficiency and in patients with Menkes disease, an X-linked disorder of copper transport due to mutations in ATP7A." (PMID 37296680, 2023). "Failure to identify a pathogenic variant in the ATP7A gene leading to birth of two boys with Menkes disease invokes the required procedures to screen and detect disease-causing gene variants." (PMID 36995557, 2023). "ATP7A mutations in Menkes disease and occipital horn syndrome indirectly affect the crosslinking of elastin by disrupting cellular copper transport and subsequent LOX activity." (PMID 37001705, 2023). "Menkes disease is a severe childhood disorder caused by pathogenic variants in ATP7A [OMIM #300011]." (PMID 36995557, 2023).
Menkes disease (continued). "Inactivation of ATP7A in patients with Menkes disease causes Cu-deficiency in the brain, numerous metabolic abnormalities (including catecholamine misbalance), delayed neurodevelopment, and death in the early childhood." (PMID 36626371, 2023). "It is thought that mutations in the ATP7A/B family, which are identical enzymes, cause the hereditary copper transport diseases Menkes and Wilson illness." (PMID 36275614, 2022). "Genetic mutations affecting ATP7A result in Menkes disease (MD), a congenital condition characterized by the enterocytes’ inability to release copper in the portal vein and generalized copper deficiency." (PMID 35267564, 2022). "MD, also known as Menkes kinky hair syndrome, is a rare X-linked recessive genetic disease of impaired copper metabolism caused by variants in ATP7A gene." (PMID 35432457, 2022). "Mosaic mutants belong to the group of mottled mutations mice, which constitute an animal model of human Menkes disease, as they display similar disturbances of copper metabolism that are observed in patients with the mutation of the X-linked Atp7a gene." (PMID 36232742, 2022). "For example, mutations in the intronic sequences of the ATPase copper transporting alpha (ATP7A) gene cause Menkes disease and occipital horn syndrome." (PMID 36237189, 2022). "The essential requirement for copper in humans is illustrated by Menkes disease, a fatal neurodegenerative disorder of early childhood caused by mutations in the ATP7A copper transporter." (PMID 35433682, 2022). "Mutation of ATP7A is demonstrated to be associated with Menkes disease, occipital horn syndrome, and X-linked distal spinal muscular atrophy." (PMID 36033443, 2022). "Menkes disease arises as a consequence of loss-of-function mutations in the ATP7A gene, which encodes ATPase Copper Transporting Alpha, causing the impaired absorption and cellular metabolism of copper." (PMID 35163523, 2022). "The essential nature of copper in humans is underscored by Menkes disease, an X-linked copper deficiency disorder caused by mutations in the ATP7A copper exporter." (PMID 35433682, 2022). "The pathological mechanisms of OHS and Menkes disease are likely conserved, with Menkes arising from a complete loss of ATP7A activity, whereas in OHS there is residual activity, resulting in a milder phenotype." (PMID 35023559, 2022). "Menkes disease (MNK) is caused by mutations in the ATP7A gene, the product of which is directly involved in copper metabolism." (PMID 33925963, 2021). "Given that classical Menkes disease is often associated with gross changes in ATP7A expression, we quantified mRNA and protein levels of ATP7A." (PMID 33359139, 2021). "The Menkes disease (MD) involves a mutation in ATP7A and leads to copper deficiency and thereby strong neurodegenerative disorders." (PMID 34207741, 2021). "Wilson’s disease and Menkes disease are neurodevelopmental disorders resulting from mutations in the copper transporters ATP7A and ATP7B, with ATP7A mutations also causing occipital horn syndrome, and distal motor neuropathy." (PMID 33359139, 2021). "Genetic variants of ATP7A are responsible for multiple diseases with neurologic and neuromuscular symptoms including Menkes disease (MD; OMIM 309400), occipital horn syndrome (OHS; OMIM 304150), and X-linked distal motor neuropathy (SMAX3, OMIM 300489)." (PMID 33359139, 2021). "Menkes disease is an X-linked recessive disorder of copper metabolism due to a mutation in the ATP7A gene that leads to copper deficiency, culminating in a severe progressive neurodegenerative disease including bowel and bladder dysfunction." (PMID 33924675, 2021). "The loss of ATPase copper-transporting alpha (ATP7A) activity, which causes Menkes disease, results in the accumulation of copper in cellular organelles, including mitochondria, thereby disrupting the mitochondrial redox balance." (PMID 33918445, 2021).